LEP (leptin)
Diseases named in the same sentence as LEP in open-access papers (continued):
Sharing a sentence is not in itself a finding about the gene and the disease.
depression (continued). "The serum levels of leptin determined at admission was the marker associated with the presence of major depression at 3 months (OR 1.21, 95% CI: 1.12–1.30; P<0.001)." (PMID 25061971, 2014). "Several studies in humans have examined the association between leptin and depression, but their results are inconsistent." (PMID 25079305, 2014). "Animal studies confirmed that a deficiency in leptin signaling is linked with depression and that leptin can act as an antidepressant, possibly via a direct action on the hippocampus." (PMID 25177272, 2014). "In older men, the combination of elevated visceral fat and high leptin levels was associated with depression onset." (PMID 24109426, 2013). "It has been reported that increased level of leptin is associated with abdominal obesity, higher risk of ischemic stroke and post-stroke depression." (PMID 23510433, 2013). "Apart from its numerous actions on physiological processes such as appetite, energy expenditure and neuroendocrine function, leptin is linked to human depression and has been shown to have antidepressant and anxiolytic effects in rodents." (PMID 24109426, 2013). "In addition, we found a positive association between leptin and depression scores in the FD group, indicating a positive effect of leptin reduction, which has been postulated previously." (PMID 40836308, 2025). "We also found associations between leptin levels and depression independently of BMI." (PMID 39529327, 2024). "Elevated leptin levels have been associated with greater severity of depression." (PMID 39335507, 2024). "The ratio of BDNF to leptin levels has been associated with treatment responses in depression and may also be related to the neuroplasticity of depression, as evidenced by a 12-week follow-up study." (PMID 39253375, 2024). "Many studies have shown that obese people have a higher risk of depression, and this may be related to increased inflammatory response, leptin resistance, cortisol-binding receptor damage, and disordered intestinal flora." (PMID 39502295, 2024). "In addition, fitness and exercise reduce leptin concentrations, elevated levels of which are implicated in the development of depression, as previously discussed." (PMID 38560580, 2024). "Weight loss in depression was caused by decreased peripheral leptin." (PMID 37041835, 2023). "Animal model data support the hypothesis that leptin insufficiency may underlie depression-like behavioral deficits." (PMID 35911226, 2022). "After adjusting for age, exercise, BMI, and parameters of lipid profiles, these associations remained significant, thus suggesting that circulating Log adiponectin and Log leptin levels may be linked to depression and anxiety symptoms in postmenopausal women." (PMID 33667284, 2021). "Leptin resistance has been associated with the atypical subtype of major depression." (PMID 33546219, 2021). "The study found Leptin-leprb plays an important role in the pathogenesis and depression of gastric cancer Leptin-leprb may be a potential diagnostic marker and therapeutic target for gastric cancer." (PMID 34491229, 2021). "Moreover, a higher ratio of pre-treatment pBDNF to leptin was associated with a greater treatment response in major depressive disorder." (PMID 32012942, 2020). "In humans, an elevated leptin level has been associated with autism and Rett syndrome, whereas a decrease in leptin is linked to schizophrenia and depression." (PMID 31413047, 2019). "Interestingly, two meta-analyses have found a significant association of elevated leptin with depression only when controlling for BMI." (PMID 30405455, 2018). "Furthermore, with respect to leptin specifically, depression is associated with low levels of this adipokine hormone and pharmacological studies indicate that leptin has antidepressant-like efficacy." (PMID 30057529, 2018). "Importantly, leptin deficiency in this period is associated with long term consequences such as cognitive defects, anxiety, and depression." (PMID 30106375, 2018).
depression (continued). "Consequently, leptin are potential therapeutic targets for treatment of depression, and elucidation of leptin-associated mechanisms underlying neural plasticity will enhance our understanding of the psychopathology of depression." (PMID 30367065, 2018). "In addition, clinical studies have shown that the expression of leptin mRNA and protein are positively associated with depression severity." (PMID 30367065, 2018). "Leptin-LepRb therefore could be a potential diagnostic marker and therapeutic target in GC patients with depression." (PMID 28316984, 2017). "Furthermore, our findings suggest that leptin changes are differently associated with weight gain and psychological symptoms such as depression, anxiety, and perceived stress depending on the severity of starvation." (PMID 28030575, 2016). "The only previous pre-post study that assessed leptin and depression simultaneously in AN patients found that higher increases in leptin from the time of admission to the time of discharge were associated with less improvements in clinician-rated depression scores." (PMID 28030575, 2016). "In addition to these findings with depression, lower serum leptin levels in women have been associated with anxiety symptoms and perceived stress." (PMID 26303856, 2015). "This pleiotropy in leptin function may allow us to identify a subgroup of pregnancies (those complicated by depression or anxiety disorders) that may be at increased risk of poor fetal growth due to a mechanism that involves altered leptin signaling." (PMID 26303856, 2015). "A second hypothesis in favor of the antidepressant role of leptin is linked to the neurotrophic hypothesis of depression, since this adipokine may facilitate neurogenesis." (PMID 25386150, 2014). "Theoretically, the association of leptin with depression may be related both to its metabolic properties and neurobiological activities." (PMID 24762259, 2014). "Leptin and ghrelin have been implicated in the pathogenesis of major depression." (PMID 25079305, 2014). "Regarding the association between depression and leptin, an adipokine mainly secreted by adipocytes with a key role in energy regulation, it seems that resistance to this hormone may contribute to higher depression rates in obese subjects." (PMID 24762259, 2014). "In a Japanese population, which has on average much lower BMI than Westerners, the association between leptin and mood disorder may be less likely to be influenced by such inflammation-depression pathway." (PMID 25079305, 2014). "White adipose tissue, especially in the abdominal area, is an active endocrine organ producing inflammatory cytokines and hormones (for example, leptin) and, therefore, a major contributor to pathogenic immunometabolic responses linked to metabolic diseases and depression." (PMID 23672628, 2013). "The association of leptin with depression could be explained not only by its metabolic properties but also by its neurobiological activity, as leptin is able to affect neuroprotection, cognition, and mood in the hippocampus, the cortex, and other brain areas." (PMID 24229349, 2013). "Deficient leptin signaling in the brain has been hypothesized to link depression and metabolic dysregulation." (PMID 23251447, 2012). "Leptin-deficient animals exhibit respiratory depression and CO2 retention." (PMID 21676224, 2011). "Perhaps unexpectedly, in humans, elevated serum leptin predicts greater risk of atypical depression, especially in individuals with high abdominal adiposity; this may, however, be caused by leptin resistance, which induces a compensatory increase in circulating leptin." (PMID 40991698, 2025). "Lastly, some studies suggest that leptin may be a biomarker of risk for de-novo depression." (PMID 38098007, 2023). "Thus, the often-described association between depression scores and leptin levels seen in elderly men might be due to this phenomenon." (PMID 35633817, 2022).
depression (continued). "Thus, the leptin/LepRb pathway may be associated with the multifactorial effects of PF against gastrointestinal disorders and depression- and anxiety-like behaviors in PI-IBS rats." (PMID 36225193, 2022). "Moreover, elevated leptin levels may be associated with depression and anxiety experienced by CF patients, requiring further investigation and multivariate analysis." (PMID 36186778, 2022). "Low leptin levels were linked to MDD in middle-aged adults while in older age, high levels were associates with depression." (PMID 35633817, 2022). "The increase in circulating leptin and, consequently, inflammation may serve as a potential explanation for the positive association since imaging studies on multiple sclerosis and depression have suggested a link between an increase in CNS inflammation and an enlarged CP." (PMID 36313760, 2022). "Additionally, the literature provides evidence that genetic factors may increase patients’ risk of disordered eating, depression, and even suicide, and hormonal factors such as cortisol and leptin may also have a role in restrictive eating and mental healt h." (PMID 34001260, 2021). "Thus, the hypothesis of this study is that dysregulation (either high or low levels) of ghrelin and leptin are associated with the level of depression symptoms in individuals with diabetics, while cortisol is positively correlated with depression symptoms." (PMID 33023555, 2020). "Alternatively, resistance to leptin may constitute a risk for depression." (PMID 31964368, 2020). "Leptin was proved previously to be positively associated with the glucocorticoids, which are responsible for the hyperactivity of the hypothalamic-pituitary-adrenal axis, increasing during depression and may cause damage to the structure of brain." (PMID 31354416, 2019). "Moreover, the prevalence of MetS is 58% higher in psychiatric patients than in the general population, with prominent anorexigenic and orexigenic hormones leptin and ghrelin identified to be associated with psychiatric disorders including schizophrenia, bipolar disorder and major depression." (PMID 30405455, 2018). "Leptin signaling is involved in the pathophysiology of major depressive disorders, exerting its effects by activation the leptin receptor, which is distributed in various brain regions such as the prefrontal cortex and hippocampus, two limbic brain areas implicated in depression." (PMID 29186207, 2017). "Therefore, leptin resistance might be implicated as a mediating factor for the association between sarcopenic obesity and depression." (PMID 27627756, 2016). "Similarly, given a large difference in blood leptin and ghrelin levels between men and women, there may be a sex difference in the association between these hormones and depression." (PMID 25079305, 2014). "In conclusion, there is a current consensus suggesting a reduced leptin signaling in human depression, even though, this association might be stronger in certain subtype of depression or might be influenced by different factors including age, sex, body mass, and co-morbidity with other disorders." (PMID 25386150, 2014). "Leptin represents a potential therapeutic target in the treatment of depression, by stimulating hippocampal neurogenesis, decreasing inflammation, and modulating synapsis plasticity." (PMID 41375608, 2025). "To reconcile the discrepancies between studies, we compared original research that specifically examined the relationship between leptin levels and clinical symptoms of depression." (PMID 40507778, 2025). "In fact, premenopausal women with depression exhibit higher nocturnal leptin in comparison to their healthy counterparts." (PMID 41375608, 2025). "Leptin receptors add another metabolic dimension: transcriptomic work in late-onset depression identified LEP as a high-accuracy diagnostic marker, linking dysregulated leptin signalling to inflammatory depression phenotypes." (PMID 41373485, 2025).
depression (continued). "Patients with mild to moderate depression exhibited significantly higher leptin levels compared to controls, suggesting a possible compensatory role of leptin in early stages of depressive illness." (PMID 40507778, 2025). "The various distribution of LEP-Rs is especially important in depression’s pathophysiology, considering that disrupted leptin signalling in the VTA and NAc, part of the brain’s reward pathway, has been associated with anhedonia, a core symptom of depression." (PMID 41375608, 2025). "Leptin is involved in the neurobiology of depression through several mechanisms, including complex intracellular signalling cascades, NMDAR regulation, modulation of BDNF expression, and brain reward circuitry functioning." (PMID 41375608, 2025). "Leptin plays a significant role in counteracting the usual neuronal atrophy that is found in depression." (PMID 41375608, 2025). "These events seem to be related to the improvement in depression status, which in turn leads to an increase in leptin levels as a compensatory mechanism." (PMID 40573133, 2025). "Leptin levels in patients with moderate to severe depression were higher than those displaying mild or minimal depression." (PMID 40565847, 2025). "Leptin increases the histone acetylation of the BDNF promoters, thus increasing the transcription of its gene, the latter process being deficient in depression." (PMID 41375608, 2025). "The scientific literature reveals discrepancies regarding the relationship between leptin levels and depression." (PMID 40507778, 2025). "Clinical studies showed positive correlations between leptin serum levels and the severity of depression." (PMID 40565847, 2025). "Our findings reveal that pregnant women experiencing perinatal anxiety and depression exhibited elevated levels of adiponectin, leptin, and resistin levels compared to healthy pregnant subjects." (PMID 40565847, 2025). "Similar to the previously discussed resistin and leptin, elevated serum levels of FetA have been observed in patients with recurrent depressive disorder compared to controls." (PMID 40507778, 2025). "The role of impaired leptin production or signaling in depression was supported by a study in which treatment of diabetic mice with leptin reversed the depressive-like behavior in the tail suspension test." (PMID 38029397, 2024). "Even after adjusting for age, sex, and ethnicity, leptin levels remain a strong predictor of depression." (PMID 39335507, 2024). "The organizational and activational effects of sex hormones contribute to such gender differences, such as the earlier pubertal onset in females or the higher leptin concentrations observed in females with major depression compared to males." (PMID 39519542, 2024). "Up to this day, leptin has been associated with the increased risk of CVD or metabolic diseases, some types of cancer, and depression." (PMID 38668349, 2024). "The review also highlights the involvement of inflammatory markers, such as Interleukin 6 (IL-6) and leptin, in PD and Major Depressive Disorder (MDD) patients." (PMID 39025836, 2024). "Further studies and meta-analyses are needed to confirm the significance of found SNPs and the role of leptin in depression." (PMID 39529327, 2024). "Depression and well-being score associations with complement component 3 (CES-D only) c-reactive protein, interleukin 6, leptin, white blood cell counts, neutrophils and the inflammatory biomarker score were observed." (PMID 38560580, 2024). "In women, leptin levels are higher than in men and this difference is significantly more pronounced in women suffering from depressive disorders." (PMID 38674096, 2024). "Some studies showed lower plasma levels of leptin in these patients; however, in cases of major depression disorder, serum concentrations were higher than in control subjects." (PMID 36674935, 2023).
depression (continued). "High consumption of processed and red meats was associated with elevated levels of low-grade inflammation (C-reactive protein) and pro-inflammatory adipokine (leptin) as well as subsequent brain atrophy which is positively correlated with depression." (PMID 37432385, 2023). "Available information about the role of leptin signaling in human depression is limited and controversial." (PMID 38098007, 2023). "Some proinflammatory cytokines and hormones (such as ghrelin, leptin, orexin, or insulin), involved in appetite and weight regulation, are cited among the neurobiological substrates of depression." (PMID 37049408, 2023). "Three metabolic hormones—insulin, leptin, and adiponectin—are integral to understanding relationships between inflammation, depression, and brain function." (PMID 37443383, 2023). "The ambiguous relationship between serum leptin levels and depression was also supported by a meta-analysis of depression." (PMID 37399205, 2023). "And after adjusting for multiple factors such as age, gender, and race, leptin levels remained a key predictor of depression." (PMID 37387537, 2023). "Leptin administration, systemically or directly to the brain, counteracts depression-related deficits related to chronic stress." (PMID 37938494, 2023). "Among the hormones secreted by adipose tissue, leptin appears to be involved with depressive disorders, including MDD and depression in BD." (PMID 36970275, 2023). "Among the hormones secreted by adipose tissue, leptin seems to be involved with depressive disorders." (PMID 36970275, 2023). "Leptin regulates synapse formation and activity in the hippocampus via the miR-132/p250GAP pathway, mitigates depression and anxiety, and improves cognitive function." (PMID 34969353, 2022). "Systemic or intracerebroventricular (ICV) administration of leptin reverses chronic stress-induced depression-related behavioral deficits including anhedonia." (PMID 36138127, 2022). "Current research offers new hope to patients with depression and anxiety by directly targeting leptin-expressing neurons to alter pathological changes." (PMID 36430254, 2022). "In humans, the relationship between leptin concentrations in blood and depression is viewed rather controversially across studies; confounders, including sex and body mass index, warrant particular attention." (PMID 36037795, 2022). "The results from our study indicate that those subjects who experience high stress, anxiety, and depression have their plasma leptin elevated." (PMID 35886710, 2022). "There is also evidence that leptin and LepRb participate in the pathogenesis of depression and anxiety." (PMID 36225193, 2022). "In line with this, CRP inhibits leptin from binding to its receptor in mice, again implicating central leptin resistance as a possible pathological mechanism for depression." (PMID 35633817, 2022). "As an important regulator during the pathogenesis of depression and inflammation, the circulating levels of leptin were found to be positively correlated with the severity of depression." (PMID 36225193, 2022). "It is known to affect biological signaling cascades implicated in depression, including the corticotrophin-releasing hormone (CRH), leptin, and the sympathetic nervous system pathways." (PMID 35017468, 2022). "The results from this study confirm that leptin knockout increases depressive-like behaviors; there was a tendency toward depression in the obese animal model." (PMID 35761401, 2022). "In general, leptin's involvement in the pathophysiology of depression is quite well documented: it decreases anxiety- and despair- behavior in mice, most likely by acting on mesolimbic neurons." (PMID 35633817, 2022). "Animal models of stress-induced depression have shown induction of low concentrations of leptin in the respective behavioral models of depression." (PMID 36037795, 2022).